SHH (sonic hedgehog signaling molecule)
Diseases named in the same sentence as SHH in open-access papers (continued):
Sharing a sentence is not in itself a finding about the gene and the disease.
medulloblastoma (continued). "Vismodegib is a ligand-specific inhibitor of the SHH pathway and has been identified as a potential drug against SHH-activated medulloblastomas." (PMID 34360713, 2021). "Intriguingly, these CGNPs are putative cells-of-origin for SHH and Group 3 medulloblastoma, which aligns with our finding that SHH and Group 3 survival most prominently correlates with CREB activity." (PMID 34373489, 2021). "Further research revealed several additional molecular markers for WNT-and SHH-activated medulloblastomas." (PMID 33497354, 2021). "Due to the rarity of medulloblastoma in adults, only thirty patients were enrolled on the study, and 67% of these had an SHH-activated tumor." (PMID 33497354, 2021). "Medulloblastoma is well understood on a molecular level, and two of the molecular subgroups, SHH and WNT, are driven by pivotal signaling pathways that are, in principle, amenable to targeted therapies." (PMID 34298664, 2021). "SHH signaling pathways have been reported to be active in medulloblastoma and GBM, and to a lesser extent in neuroblastoma." (PMID 34012965, 2021). "A total of 250 miRNAs were screened in 31 primary medulloblastoma specimens and 34 miRNAs differentially expressed between SHH-MB versus WNT-MB, Grp3-MB and Grp4-MB were identified." (PMID 34944941, 2021). "Recently, a phosphorylated form of ATOH1 was found in human SHH-activated medulloblastoma samples and serves to stabilize ATOH1, leading to increased ATOH1-mediated activity and proliferation of tumor initiating cells." (PMID 34012965, 2021). "SOX2 is also overexpressed or amplified in oligodendrogliomas and GBMs, and interestingly appears to be more highly expressed in the SHH-activated subgroup of medulloblastomas, perhaps suggesting a link between SHH and SOX2 signaling in a neoplastic context." (PMID 34012965, 2021). "INPP5E, encoding inositol polyphosphate-5-phosphatase, promotes sonic hedgehog (SHH) signaling in SHH medulloblastoma by negatively regulating a phosphoinositide 3-kinase (PI3K) signaling axis that maintains primary cilia on tumor cells." (PMID 34760709, 2021). "Patient characteristics for the Gorlin M0 Cohort (all genetically diagnosed PTCH1 and SUFU associated Gorlin syndrome patients) vs. the Comparative M0 Cohort (all medulloblastomas (MB), SHH+, M0, <4y)." (PMID 34888241, 2021). "SHH also contributes to proliferation, and these authors showed that it is downregulated in medulloblastoma cells in vitro." (PMID 34436033, 2021). "The findings in this study demonstrate significant differences in the tumor microenvironment between medulloblastoma subgroups, with the SHH-subgroup enriched in the stromal population while group 3 is comparatively stroma-suppressed." (PMID 34667228, 2021). "SHH-activated medulloblastomas can be treated with vismodegib as a targeted therapeutic agent, and the drug is available orally." (PMID 33497354, 2021). "In this study, we used publicly available gene expression profiling datasets from a human medulloblastoma cell line that possesses a fully inducible endogenous SHH pathway according to gene expression profiling." (PMID 32341755, 2020). "Among the SHH pathway genes, PTCH1 was mutated in 36% (12/33) of adult SHH medulloblastomas, and SMO was mutated in 27% (9/33)." (PMID 33172502, 2020).
medulloblastoma (continued). "Especially for SHH-dependent medulloblastoma where more direct SHH pathway drugs, including SMO inhibitors, are shown to induce severe side effects in young children or infants." (PMID 33585252, 2020). "PAX6 participates neuronal fate determination and can be regulated by SHH signaling in medulloblastoma." (PMID 32508873, 2020). "Another striking feature of adult WNT medulloblastomas is the concurrent mutations of WNT and SHH pathway genes." (PMID 33172502, 2020). "SHH-driven medulloblastoma is characterized by altered SHH/Gli signaling which regulates stem cell properties in CSCs." (PMID 33297302, 2020). "The prognosis of SHH-activated and G4 medulloblastomas is worse than WNT, with 5-year OS rate of 75% and 70%, respectively, whereas that of G3 has the most unfavorable 5-year overall of 50%." (PMID 33343359, 2020). "Aberrations in SHH signaling, especially PTCH1 gene mutations leading to constitutively activated Smo, are found in ~25% of medulloblastoma." (PMID 33066274, 2020). "Knockout of Trim32 resulted in a higher incidence of medulloblastoma formation in the Ptch1 ± mice and the upregulation of SHH target genes, suggesting a tumor suppressor effect from antagonizing SHH signaling." (PMID 33273457, 2020). "Advanced genomic research has led to the accumulation of an enormous amount of genetic information and resulted in a consensus distinguishing four molecular subgroups, WNT-activated, SHH-activated, and Group 3 and 4 medulloblastomas." (PMID 31970590, 2020). "Taken together, miR-326 and its host protein, ARRB1, function together to negatively regulate SHH/Gli signaling in medulloblastoma CSCs in a complementary manner." (PMID 33297302, 2020). "SHH is the predominant group in adult medulloblastomas, and adult SHH tumours are characterised by upstream pathway mutations in PTCH1 and SMO, whereas downstream pathway alterations such as SUFU mutations and MYCN amplifications are rare in this age group." (PMID 33172502, 2020). "Although the data are currently limited to individual objective responses in small cohorts the most promising and mature targeted approach is to use the SMO inhibitors sonidegib or vismodegib in SHH-driven medulloblastoma, preferably within clinical trials." (PMID 32676456, 2020). "We confirmed that there were 1 WNT, 2 SHH, 3 Group 3 and 4 Group 4 medulloblastoma through class prediction analysis." (PMID 33292274, 2020). "Activating SHH-pathway mutations in CGNPs cause medulloblastomas in genetically engineered mice, identifying CGNPs as the cell of origin for SHH-driven medulloblastoma and providing a primary animal model of the human disease." (PMID 31863004, 2019). "One of these medulloblastoma groups displays activation of Sonic hedgehog (SHH) signaling and originates from granule cell precursors of the developing cerebellum." (PMID 31700613, 2019). "Given that cilia are required for proper SHH signaling, INPP5E loss disrupts the progression of SHH-dependent medulloblastoma." (PMID 31413155, 2019). "Recently, from a 960-compound screening, quisinostat and other class I HDAC inhibitors are found to suppress growth of diverse SHH signaling inhibitor-resistant clones of mouse medulloblastoma cells." (PMID 31788346, 2019). "Approximately 25% of medulloblastomas belong to the SHH subgroup, characterized by aberrant SHH signaling." (PMID 31554835, 2019). "Of these subgroups, SHH remains one of the most studied tumour groups due to the ability to model medulloblastoma formation through targeted deletion of the Shh pathway inhibitor Patched1 (Ptch1)." (PMID 30657775, 2019).
medulloblastoma (continued). "Developmental pathways such as SHH are often co-opted by cancer, and this is true for SHH medulloblastoma." (PMID 31541170, 2019). "The role of GRK2 in SHH/Smoothened signaling in invertebrate development and in mammalian cells suggest a potential link to medulloblastoma." (PMID 31554835, 2019). "Mocetinostat (MGCD0103), an HDAC1/HDAC2 inhibitor, is found to target Gli1 acetylation to truncate SHH signaling in medulloblastoma cells." (PMID 31788346, 2019). "Roughly one-third of medulloblastoma are driven by aberrant activation of the Sonic Hedgehog (SHH) signaling pathway." (PMID 31541170, 2019). "Using single-cell RNA-seq and lineage tracing, we analyzed cellular diversity in medulloblastomas in transgenic, medulloblastoma-prone mice, and responses to the SHH-pathway inhibitor vismodegib." (PMID 31863004, 2019). "In 2012, an international consensus paper reported that medulloblastoma comprises four molecular subgroups (WNT, SHH, Group 3, and Group 4), each associated with distinct genomic features and clinical behavior." (PMID 31076851, 2019). "The 20 medulloblastoma models in this cohort span all broad subtypes: SHH (n = 7), WNT (n = 2), group 3 (n = 7), and group 4 (n = 3), and one model without RNA-seq remained unclassified." (PMID 31693904, 2019). "Thirty percent of medulloblastomas show hyperactivation of the SHH signaling pathway, which also drives the normal proliferation of cerebellar granule neuron progenitors (CGNPs) during cerebellar development." (PMID 31863004, 2019). "Consistent with a direct mechanism, SMOM2-mediated SHH hyperactivation clearly correlated with increased Hes1 expression, as Hes1+ cells were markedly enriched in M-Smo medulloblastomas compared to WT P7 cerebella." (PMID 31863004, 2019). "Patients with Turcot’s syndrome, who have a germline mutation in the adenomatous polyposis of the colon (APC) gene, are predisposed to WNT-subtype medulloblastoma, which has a more indolent clinical course than SHH-subtype medulloblastoma." (PMID 31204176, 2019). "Direct stimulation of Hes1 by SHH would be clinically relevant as it would limit the potential for NOTCH-pathway inhibitors to alter medulloblastoma growth." (PMID 31863004, 2019). "Targeting oncogenic pathways holds promise for brain tumor treatment, but inhibition of Sonic Hedgehog (SHH) signaling has failed in SHH-driven medulloblastoma." (PMID 31863004, 2019). "The most prevalent subclass of medulloblastoma is Sonic Hedgehog (SHH), comprising 30% of all cases." (PMID 31160587, 2019). "Classification of tumors based on genetic and phenotypic characteristics has resulted in the division of medulloblastoma into four main subgroups, one of which is driven by aberrant Sonic Hedgehog (SHH) pathway activity." (PMID 31541170, 2019). "We examined the effects of PI3Kα and mTOR inhibition on GLI1 nuclear accumulation in SHH-driven medulloblastoma using nuclear/cytoplasmic fractionation of DAOY cells with Lamin A/C and tubulin as nuclear and cytoplasmic loading controls, respectively." (PMID 31492956, 2019). "Conditional knockout of Ptch1 in GNP cells led to the formation of medulloblastoma in all mice by 3 months of age, confirming that GNP cells are susceptible to oncogenic transformation in the context of SHH overactivity." (PMID 31204176, 2019). "Here, we investigate loss of AMPKα2 in a genetically engineered mouse model of sonic hedgehog (SHH)-medulloblastoma." (PMID 30360486, 2018). "Immunophenotypic characterization and methylation profiling suggested a medulloblastoma with SHH activation." (PMID 29971034, 2018). "Together, these observations are in agreement with a pro-tumorigenic role for the SHH/AMPK/CNBP axis in medulloblastoma." (PMID 30360486, 2018). "Cholesterol plays a central role in the regulation of SHH signalling in medulloblastoma and normal cells." (PMID 29352211, 2018).
medulloblastoma (continued). "The large majority of children with WNT-medulloblastomaa and ~75% of those with SHH-medulloblastomas are cured with the current therapy treatments (surgery and chemoradiotherapy)." (PMID 30279357, 2018). "Because of its clinical utility, a molecular classification into four groups has been formulated: group I, Wnt-activated medulloblastoma; group II, SHH (Sonic Hedgehog)-activated medulloblastoma; group 3 and 4 composed of so called non-Wnt/non-SHH tumors." (PMID 29584702, 2018). "Based on these and other observations, medulloblastoma is now considered as comprised of at least four main subgroups with distinctive molecular, demographic and clinical characteristics, termed SHH, WNT, group 3 and group 4 medulloblastoma variants." (PMID 30314361, 2018). "As we have seen from various reports, targeting the SHH pathway for inhibition using vismodegib led to increased frequency of quiescent Sox2+ medulloblastoma cells in the Ptch+/− mouse models." (PMID 29298329, 2018). "Through this we will be able to efficiently differentiate and identify markers for therapeutic response between NSCLC‐ squamous and ‐adenocarcinoma; among Wnt‐, SHH‐, Group‐3‐ and Group‐4‐Medulloblastoma; and between TKI sensitive and TKI‐resistant CML cases." (PMID 29460395, 2018). "Subsequently, the increased level of CNBP protein expression results in the increased translation of ODC1 and associated activation of polyamine metabolism, which is essential for the SHH-dependent proliferation of medulloblastoma cells." (PMID 30360486, 2018). "Second, a potential tumor-suppressive role for AMPK in SHH-driven medulloblastoma was also inferred by the fact that the increased survival observed upon Hk2 KO in a mouse model of medulloblastoma is accompanied by a gain of AMPK activity." (PMID 30360486, 2018). "This behaviour, which is highly reminiscent of lineage progression during neural development, has also been proposed for SHH-driven medulloblastoma." (PMID 29759978, 2018). "GNAS activity was shown to suppress SHH signaling and loss of GNAS in neural stem/progenitor cells induces medulloblastoma formation with full penetrance." (PMID 30279357, 2018). "In SHH-driven medulloblastoma tumorigenesis, several studies support a tumor-suppressive role for AMPK." (PMID 30360486, 2018). "Molecular studies have allowed for the identification of a SHH-subtype medulloblastoma and a WNT-subtype." (PMID 30279357, 2018). "For instance, mutations in PTCH1, SMO or SUFU and somatic amplification of GLI2 and MYCN, all deregulating Sonic hedgehog (SHH) signalling, define subgroup 2 medulloblastoma (or ‘SHH' subgroup)." (PMID 30100614, 2018). "In one study, ABCA8 was found to be upregulated in a subtype of medulloblastoma defined as Sonic hedgehog (SHH) and downregulated in the subtype defined as Wnt signaling." (PMID 29324814, 2018). "According to these observations it was concluded that oncogenic SHH signaling promotes medulloblastomas from progenitor cell populations." (PMID 30279357, 2018). "We analysed the expression of the SCARB1 gene in medulloblastoma, a tumour driven by aberrant activation of the SHH signalling pathway." (PMID 29352211, 2018). "Based on this finding, Xu and colleagues investigated the consequence of PIN1 inhibition on SHH-medulloblastoma tumorigenesis in vivo." (PMID 30314361, 2018). "Here, we focus on targeting sonic hedgehog (SHH) subtype medulloblastoma, which accounts for approximately 25% of all cases." (PMID 29352211, 2018). "In summary, we present a novel application of HDL NPs for the treatment of SHH-driven medulloblastoma." (PMID 29352211, 2018).
medulloblastoma (continued). "Further association with mutations of the BCL6 repressor gene BCOR, commonly altered in medulloblastomas, neuroepithelial tumors, and sarcomas, highlights a further avenue for interventional study through its regulation of the SHH pathway." (PMID 28966033, 2017). "SHH has been related to both basal cell carcinoma and medulloblastoma which, in some forms, have amplification of the MYCN locus." (PMID 28358317, 2017). "Microarray analysis from human medulloblastoma patients indicates significant upregulation of the gene expression levels in medulloblastoma for a number of known target proteins for 4SC-202 and SHH pathway proteins." (PMID 29099739, 2017). "Here, we analyse the global levels and spatial distribution of 5hmC and 5caC in four brain tumour cell lines derived from paediatric sonic hedgehog (SHH) pathway-activated medulloblastomas (Daoy and UW228-3) and ependymomas (BXD-1425EPN and DKFZ-EP1NS)." (PMID 28228863, 2017). "The distinction of four molecular subgroups depends on the transcriptional profiles of the subgroups, which at least for SHH subtype reflects the cells of origin of the medulloblastoma." (PMID 27234298, 2016). "Much is known about the cells of origin and the driving pathways of WNT and SHH medulloblastomas, but Group 3 tumors are less well characterized." (PMID 26883117, 2016). "In medulloblastoma, SHH/Gli has been shown to drive expression of stem cell modulator Bmi1, a key transcriptional polycomb repressor, found to be overexpressed in medulloblastoma and in CD133+ tumor initiating progenitors." (PMID 27043632, 2016). "Recent studies have shown that SHH signaling is abnormally activated in neuroblastoma, colorectal cancer, basal cell cancer, medulloblastoma, prostate cancer, ovarian cancer, pancreatic cancer, and other forms of cancer." (PMID 27039174, 2016). "Zeb1 expression is elevated in the Sonic Hedgehog (SHH) medulloblastoma subgroup originating from GNPs with persistent SHH activation." (PMID 27178982, 2016). "Activating mutations in the key components of the SHH pathway PTCH1, SMO and SUFU have been described in medulloblastoma and basal cell carcinoma." (PMID 27825128, 2016). "Mutations within the drug-binding pocket of the Smoothened (SMO) receptor are reported among basal cell carcinoma (BCC) and medulloblastoma patients who become resistant to the SHH/SMO inhibitor, Vismodegib." (PMID 27608848, 2016). "According to the gene transcription profiles, four different subtypes of medulloblastoma have been described, that is, wingless type (Wnt), Sonic Hedgehog (SHH), group 3, and group 4." (PMID 27234298, 2016). "Treatment of medulloblastomas in mice with an anti-mitotic drug or sonic hedgehog (SHH) pathway inhibitor resulted in residual tumors that were enriched in SOX2+ cells, indicating that these cells were likely to contribute toward tumor relapse." (PMID 27791206, 2016). "Various clinical reports suggest that SHH- driven medulloblastoma patients treated with Smo antagonists, initially show dramatic tumor regression followed by rapid tumor recurrence." (PMID 26938241, 2016). "Similar to medulloblastoma, mRNA and protein levels of SHH and GLI1 were downregulated with curcumin treatment." (PMID 27807473, 2016). "In related studies, deletion of the alpha subunit of the stimulatory heterotrimeric G protein Gs also resulted in SHH-driven medulloblastoma." (PMID 26283963, 2015).